COPG1 (coat protein complex I subunit gamma 1)
Description:
The coatomer is a cytosolic protein complex that binds to dilysine motifs and reversibly associates with Golgi non-clathrin-coated vesicles, which further mediate biosynthetic protein transport from the ER, via the Golgi up to the trans Golgi network. Coatomer complex is required for budding from Golgi membranes, and is essential for the retrograde Golgi-to-ER transport of dilysine-tagged proteins. In mammals, the coatomer can only be recruited by membranes associated to ADP-ribosylation factors (ARFs), which are small GTP-binding proteins; the complex also influences the Golgi structural integrity, as well as the processing, activity, and endocytic recycling of LDL receptors. Required for limiting lipid storage in lipid droplets. Involved in lipid homeostasis by regulating the presence of perilipin family members PLIN2 and PLIN3 at the lipid droplet surface and promoting the association of adipocyte triglyceride lipase (PNPLA2) with the lipid droplet surface to mediate lipolysis (By similarity).
Synonyms: COPG; IMD128
Tractability: Antibody: UniProt places it where antibodies can reach, with high confidence. PROTAC: ubiquitination databases record sites on it; its protein half-life has been measured.
Gene: Protein-coding gene on chromosome 3 (129,249,576 to 129,278,065, forward strand). Ensembl gene ENSG00000181789.
Subcellular location: Cytoplasm; Golgi apparatus membrane; Cytoplasmic vesicle, COPI-coated vesicle membrane
Subcellular location (Human Protein Atlas): Golgi apparatus; Cytosol; Nucleoplasm
Pathways (Reactome):
Vesicle-mediated transport: COPI-dependent Golgi-to-ER retrograde traffic; COPI-mediated anterograde transport
Gene Ontology:
Molecular function: protein binding; structural molecule activity
Biological process: endoplasmic reticulum to Golgi vesicle-mediated transport; establishment of Golgi localization; intra-Golgi vesicle-mediated transport; organelle transport along microtubule; protein secretion; retrograde vesicle-mediated transport, Golgi to endoplasmic reticulum; intracellular protein transport; vesicle-mediated transport
Cellular component: Golgi apparatus; COPI vesicle coat; cytosol; endoplasmic reticulum; endoplasmic reticulum membrane; endoplasmic reticulum-Golgi intermediate compartment; Golgi membrane; transport vesicle; COPI-coated vesicle membrane; cytoplasm; membrane coat
Genetic constraint (gnomAD): Loss-of-function variants: 26 observed, 95.83 expected, observed/expected ratio (o/e) 0.27, 90% interval 0.2 to 0.38. The upper end of that interval is the gene's LOEUF score, 0.38, which puts it in group 1 of 6, group 1 being the genes least tolerant of losing a copy. Missense variants: 812 observed, 1,107.9 expected, observed/expected ratio (o/e) 0.73, 90% interval 0.69 to 0.78. Synonymous variants: 380 observed, 419.85 expected, observed/expected ratio (o/e) 0.91, 90% interval 0.83 to 0.99.
Homologues: Orthologues: macaque COPG1 (100% identical), rabbit COPG1 (99% identical), chimpanzee COPG1 (99% identical), dog COPG1 (99% identical), guinea pig COPG1 (97% identical), mouse Copg1 (97% identical), rat Copg1 (97% identical), pig COPG1 (92% identical), tropical clawed frog copg1 (89% identical), Drosophila melanogaster gammaCOP (61% identical), Caenorhabditis elegans copg-1 (56% identical). Paralogues in human: COPG2 (81% identical).
Diseases named in the same sentence as COPG1 in open-access papers:
COPG1 is named in the same sentence as 15 diseases in open-access papers, as found by Europe PMC text mining. Sharing a sentence is not in itself a finding about the gene and the disease. The quoted sentences say what the papers report.
breast carcinoma (1 paper, 2024). "For the protein COPG1, an increased level was associated with increased breast cancer risk, with a p value of 8.54 × 10–4." (PMID 39468330, 2024). "COPG1 was associated with an increased risk of breast cancer with a p value of 8.54 × 10–4." (PMID 39468330, 2024). "Among these five proteins, the corresponding genes for three proteins, including COPG1, DCTN3, and DDX6, were located at least 1Mb away from the GWAS-identified breast cancer risk variants." (PMID 39468330, 2024). "Among these five proteins, the corresponding genes for proteins COPG1, DCTN3, and DDX6 were located at least 1 Megabase away from the GWAS-identified breast cancer risk variants." (PMID 39468330, 2024). "In this first breast-tissue-based PWAS of breast cancer risk, we found that five proteins (COPG1, DCTN3, LSP1, DDX6, and DNAJA3) were significantly associated with overall breast cancer risk." (PMID 39468330, 2024). "COPG1 was not reported in TWAS or PWAS for breast cancer, but reducing the expression of the COPG1 gene lessened the accumulation of full-length nuclear c-MET, a receptor tyrosine kinase commonly overexpressed in various malignant cancers, including breast cancer." (PMID 39468330, 2024).
COPA syndrome (1 paper, 2022). "However, since levels of type I IFN and ISGs were not measured in COPG1 (K652E) patients and the clinical presentation does not overlap with symptoms of COPA syndrome, no conclusion about contribution of a STING-driven pathology can be drawn." (PMID 35484149, 2022).
embryonal carcinoma (1 paper, 2020). A non-seminomatous malignant germ cell tumor characterized by the presence of large germ cells with abundant cytoplasm resembling epithelial cells, geographic necrosis, high mitotic activity, and pseudoglandular and pseudopapillary structures formation. "To examine whether a differential expression of Copg1 and Copg2 is also observed in another neuronal differentiation system we then analyzed mRNA and protein levels of the two γ-COP paralogs in P19 embryonal carcinoma cells." (PMID 32665377, 2020).
hepatocellular carcinoma (1 paper, 2026). A malignant tumor that arises from hepatocytes. "Functional validation in hepatocellular carcinoma revealed that COPG1 knockdown impaired malignant phenotypes and reduced tumorigenicity in vivo." (PMID 41751842, 2026).
Immunodeficiency (1 paper, 2022). Failure of the immune system to protect the body adequately from infection, due to the absence or insufficiency of some component process or substance. "This suggests defective innate immune defence mechanisms upon lost function of COPA and COPG1, which could perhaps contribute to immunodeficiency of COPG1 (K652E) patients." (PMID 35484149, 2022).
lung adenocarcinoma (1 paper, 2016). A carcinoma that arises from the lung and is characterized by the presence of malignant glandular epithelial cells. "Of the 16 distinguishing proteins, 8 were significantly elevated in lung adenocarcinoma (COPG1, STOML2, HYOU1, PDIA4, EPRS, APEX1, LRPPRC and NANS) whereas 8 proteins were significantly decreased in lung adenocarcinoma (SPTB, SPTA1, ANK1, SLC4A1, HBG1 and HBG2)." (PMID 27799870, 2016).
virus infection (1 paper, 2021). "It should also be noted that COPG1 depletion affected the viability of cells, which in turn could reduce their ability to support early stages of virus infection." (PMID 33975940, 2021).
cancer (3 papers, 2012 to 2026). A tumor composed of atypical neoplastic, often pleomorphic cells that invade other tissues. "Integrative functional dependency analyses identified COPG1 as selectively essential in multiple cancers, and its loss was associated with increased drug sensitivity." (PMID 41751842, 2026). "Expression analyses revealed broad upregulation of coatomer genes across cancer types, with COPG1 and COPB1 emerging as strong risk-associated genes (HR > 2)." (PMID 41751842, 2026). "Collectively, this pan-cancer analysis reveals the context-dependent roles of coatomer subunits and identifies COPG1 as a novel oncogenic driver and potential therapeutic target in HCC, mediating chemoresistance through redox modulation and PI3K-AKT pathway inhibition." (PMID 41751842, 2026). "EPRS was repeatedly elevated in adenocarcinoma relative to control in 79% of cancer subjects, whereas both LRPPRC and COPG1 were consistently elevated in 76% of subjects." (PMID 27799870, 2016). "Reduced expression of COPA, COPB1, COPB2, COPG1, COPD, and COPZ1 induced the punctate GFP-LC3 formation in MDA-MB-231, MDA-MB-468 and SKOV3 cancer cell lines." (PMID 22745748, 2012).
infection (3 papers, 2021 to 2025). The state of being infected such as from the introduction of a foreign agent such as serum, vaccine, antigenic substance or organism. "In line with our entry and DNA replication studies, few of the virus proteins tested were detectable in COPG1-depleted cells, confirming that this infection had been blocked at very early stages of infection." (PMID 33975940, 2021). "In addition, a lack of copG1 led to suppressed expression of nopX, nopP, and dct, which are important for infection and nodulation during symbiosis." (PMID 38927295, 2024).
tumor (3 papers, 2016 to 2022). "This may also provide a basis for the tumor-associated elevation in EPRS, which was positively correlated with LRPPRC and COPG1." (PMID 27799870, 2016). "More importantly, FERMT2 was found to be significantly underexpressed in tumor tissues, and COPG1 was slightly overexpressed in tumor tissues; thus, it was expected that FERMT2 was a positive predictor for overall survival and that COPG1 was a risk factor for disease-free survival." (PMID 33850477, 2021). "In neoantigen vaccine studies, PD-1 ICB improved MC38 tumor control elicited by nanoparticle complexes of CpG and neoantigens, including the MC38 neoantigens Adpgk and Copg1 and mutant KRAS neoantigens." (PMID 35651800, 2022). "B4GALT4, BCL2L1, COPG1, CRB3, GET4, and TFRC showed almost the same expression levels between tumor and normal tissues." (PMID 33850477, 2021).
adenocarcinoma (1 paper, 2016). A common cancer characterized by the presence of malignant glandular cells. "HYOU1 and NANS were both positively correlated with adenocarcinoma-associated increases in EPRS, which was also positively associated with LRPPRC and COPG1." (PMID 27799870, 2016). "NANS, COPG1 and PDIA4 were all negatively associated with adenocarcinoma-dependent reductions in PTRF, which was generally decreased in adenocarcinoma compared to control tissue (89% of patients)." (PMID 27799870, 2016). "Consistent with our proteomic data, mRNA expression of APEX1, HYOU1, PDIA4, NANS, LRPPRC, EPRS and COPG1 were significantly (Mann–Whitney U < 0.05) higher in adenocarcinoma compared to control whereas mRNA abundance of HBG1, HBG2, HBD, and PTRF were significantly (Mann–Whitney U < 0.05) lower." (PMID 27799870, 2016).
mental illness (1 paper, 2023). "The role of the COPG1 protein in the development of mental illness has not yet been studied." (PMID 37894929, 2023).
COPG1 also shares sentences with these, for which no sentence is quoted: bladder cancer (1 paper); primary immunodeficiency disease (1); Symbiosis (1).